IL13 (interleukin 13)
Diseases named in the same sentence as IL13 in open-access papers (continued):
Sharing a sentence is not in itself a finding about the gene and the disease.
asthma (continued). "Recently, studies on asthma indicated increased serum levels of pro-inflammatory cytokines such as IL-12, IL-13, IL-17 in individuals with asthma, which were elevated in patients with ASD as well." (PMID 27257919, 2016). "The authors state that IL-33 induction directly correlates with viral load and IL-5 and IL-13 levels, proposing IL-33 inhibition as a novel therapeutic approach for virus-induced asthma exacerbations." (PMID 27334012, 2016). "Intriguingly, genetic deletion of CD11c+ cells in a murine model of asthma (recombinant IL‐13‐induced) blocked pulmonary CCL17 production and profoundly reduced airway lymphocyte accumulation." (PMID 27621809, 2016). "Patients with this profile are the commonest participants included in recent asthma studies for novel T2-inflammation focused therapeutics, e.g. anti-IL-13 and anti- IL-5 monoclonal antibodies." (PMID 27978840, 2016). "IL-13 had been previously shown in lung fibroblasts to induce collagen through TGF-β in fibroblasts from asthma patients." (PMID 27113293, 2016). "IL-4 and IL-13 are thought to play a crucial role in Th2-characterized inflammatory diseases such as asthma and atopic dermatitis." (PMID 27491073, 2016). "In an animal model of asthma using DPP4 (CD26)-deficient rats, it was reported that CD4-positive T-cell migration decreased even with IL-13 stimulation." (PMID 26975422, 2016). "To investigate the anti-asthmatic effects of picroside II, we determined the levels of inflammatory cytokines, such as Th1 cytokine (IFNγ), Th2 cytokines (IL-4, IL-5, and IL-13), and asthma related cytokine (IL-33) in the BALF using ELISA kit." (PMID 27870920, 2016). "A notable difference was that dexamethasone was more potent than PIK-294 and tofacinib for inhibition of IL-13 from both asthma and healthy subjects, with at least 10-fold lower IC50 values." (PMID 27716212, 2016). "Asthma is typically thought to be marked by a shift towards Th2-dependent processes, both an early-phase response involving IL-4 and IL-13 and a late-phase response involving IL-5." (PMID 27965775, 2016). "Given its well-established role in modulating Th2 immune responses in AR and asthma, great efforts have been taken to investigate the modulation of IL-13." (PMID 27187364, 2016). "Low levels of IL-17 in conjunction with IL-13 are found to exacerbate asthma, while high levels of IL-17 with IL-13, are found to resolve the inflammation and resolve AHR." (PMID 27303404, 2016). "For example, elevated levels of serum periostin, an extracellular matrix protein induced by IL-4 and IL-13 in airway epithelium, identified a subset of asthma patients who responded better to lebrikizumab, an anti-IL-13 monoclonal antibody." (PMID 26993628, 2016). "In our present study, we observed a significantly decreased IL-13 level in lung homogenates of Suhuang treatment groups, which should contribute to the overall protective effects in the asthma model." (PMID 26861679, 2016). "More specifically, Tbet deficient T cells have been shown to drive airway IL-4 production and hyperreactivity in an asthma model and both IL-13 and IL-17A have been shown to be able to drive allergic airways disease in Tbet deficient mice." (PMID 27683080, 2016). "Various studies are therefore primarily focused on products that have the potential to reduce IgE, IL-4, IL-5, IL-13 and eosinophils as therapeutic targets for asthma treatment." (PMID 27255587, 2016). "The low nanomolar IC35 values of dexamethasone for IL-13 in asthma patients should be noted, but the maximal efficacy at the higher concentrations was only approximately 75 % inhibition, compared to over 90 % in healthy samples." (PMID 27716212, 2016). "Targeted therapies at IgE, interleukin-4 (IL-4), IL-4 receptor, IL-5, IL-13, tumor necrosis factor-α, and CRTh2 are new treatment paradigms for asthma." (PMID 27274620, 2016).
asthma (continued). "In our study, a thorough investigation using microarray analysis, qPCR and ELISA was conducted and we found that DPP4 expression and production were induced in both BECs from asthma patients and in cultured BECs stimulated by IL-13." (PMID 26975422, 2016). "First, DPP4 expressions were enhanced in the BECs of asthma patients, especially in snBA, and also in BECs stimulated by IL-13." (PMID 26975422, 2016). "Antigen-activated CD4+ T cells induce several characteristic features of asthma, including the secretion of Th2-type cytokines such as IL-4, IL-5, and IL-13, which are responsible for IgE production by B cells and eosinophil activation and recruitment." (PMID 26385707, 2015). "In sharp contrast, B7-H3 KO mice developed severe ovalbumin (OVA)-induced asthma with characteristic infiltrations of eosinophils in the lung, increased IL-5 and IL-13 in lavage fluid, and elevated IgE anti-OVA antibodies in the blood." (PMID 26065426, 2015). "Careful enumeration of the levels of IL-4, IL-5, and IL-13 together and the levels of eosinophils in serum and tissue can classify asthma endotypes into Th2hi and Th2lo subsets." (PMID 26346739, 2015). "Compared to Eos-Normal asthma, Eos-High asthma had higher levels of IL-5 (p<0.05), IL-13 (p<0.05), IL-16 (p<0.05), and PDGF-bb (p<0.05), but same % neutrophils, IL-8, other cytokines (data not shown), and FEV1." (PMID 26011707, 2015). "IL-33 plays significant roles in the pathogenesis of asthma, and IL-13 can be induced by IL-33 via ST2 signaling." (PMID 26610488, 2015). "Several animal models have indicated that IL-13 mediates features of asthma such as airway hyper-reactivity, mucus cell hyperplasia, and sub-epithelial airway fibrosis independent of other cytokines." (PMID 25848896, 2015). "Taken together, these reports indicate that improper bronchial epithelial repair causes a persistent repair phenotype with overproduction of inflammatory mediators and cytokines, including TGF-β and IL-13 which are central mediators of asthma." (PMID 25890309, 2015). "Based on this concept, pitrakinra, an IL-4Ra double mutein involved in both IL-4 and IL-13 signalling, was developed and tested in asthma clinical trials with favourable results." (PMID 26101468, 2015). "The four asthma-related biomarkers are periostin and interleukin 13 (IL-13), chitinase-like protein (YKL-40), and interleukin 6 (IL-6)." (PMID 26673104, 2015). "‘IL‐13 and IL‐5 high responders’ were at much higher risk of HDM sensitization and asthma compared to all other classes, with 88% of children assigned to this class being sensitized and 28.5% having asthma." (PMID 26061524, 2015). "In experimental asthma, transfer of lung basophils worsens ongoing Th2 responses by increasing airway inflammation and local IL-4 and IL-13 expression." (PMID 26284078, 2015). "Inflammatory cytokines such as IL-4, IL-5 and IL-13 are induced in the lung during asthma exacerbations." (PMID 26048391, 2015). "Various studies have shown that Th type 1 (Th1)-related cytokines (interleukin [IL]-12 and IFN-γ), Th type 2 (Th2)-related cytokines (IL-4, IL-5, and IL-13), and proinflammatory cytokines (IL-1β, IL-6, and TNF-α) are associated with asthma." (PMID 25658604, 2015). "MiR-21 was previously found overexpressed in the allergic lungs of diverse asthma mice models (transgenic IL-4 and IL-13 mice, wild-type mice treated with allergen, IL-4 or IL-13), and was induced by IL-4 in B cells." (PMID 25909590, 2015). "Even in CRSwNP patients with asthma, bronchial inflammation was ambiguous and characterized mainly by higher bronchial IL-13." (PMID 26132710, 2015). "In our previous studies using murine models of asthma, the recovery of IL-4, IL-5 and IL-13 in bronchoalveolar lavage (BAL) fluid from female mice was significantly higher than that of male mice." (PMID 26488300, 2015). "None of the measured cytokines were significantly increased in the bronchi of CRSwNP patients except for IL-13 in CRSwNP patients with asthma." (PMID 26132710, 2015).
asthma (continued). "Further, decline in the levels of IL-4, IL-5 and IL-13 cytokines and IgE was noted in the animals suffering from asthma." (PMID 26481184, 2015). "The anti-IL-13 IgG4 monoclonal antibody lebrikizumab was compared to placebo in uncontrolled asthma patients." (PMID 25671117, 2015). "Representing heterogeneous entities, in the most phenotype of asthma, type 2 immune responses are up-regulated with elevated levels of IL-4, IL-5, IL-13 and GM-CSF, whereas also pro-inflammatory TH1 cytokines and adipokines have been found elevated." (PMID 25781614, 2015). "Like our study that was also performed on unconcentrated BAL fluids using multiplex beads, these studies reported that IL-4 and IL-13 were undetectable in unconcentrated BAL fluids in asthma." (PMID 26011707, 2015). "The Th2 cytokines IL-4, IL-5, and IL-13 are the major cytokines for development of atopic diseases, such as asthma, rhinitis, and dermatitis." (PMID 26064160, 2015). "Th2 cytokines, especially IL-4 and IL-13, are crucial mediators of asthma, and both are proved to play an important role in up-regulating the eosinophil chemo-attractants of eotaxin." (PMID 26035827, 2015). "Subcutaneous injection with perilla seed water/ethanol extract, as a traditional oriental therapeutic herbal acupuncture, seemed to reduce IgE, IL-4, IL-5, and IL-13 in BALF in OVA-induced asthma in mice." (PMID 26064160, 2015). "Previous studies have shown that IL-13 is an essential factor for the development of asthma and can be produced by airway epithelial cells." (PMID 26610488, 2015). "Th2 cells distinguish themselves from other T cell subsets by secreting IL-4, IL-5, and IL-13; they actively promote IgE antibody production and regulate the immune response to allergens, including those involved in asthma and parasitic infections." (PMID 26065426, 2015). "IL-13 is a potential therapeutic target for various diseases, such as asthma and ulcerative colitis." (PMID 26317423, 2015). "Underscoring the importance of this pathway are monoclonal antibodies against IL-13 and IL-4Rα that have shown considerable promise in early phase asthma clinical trials." (PMID 26605551, 2015). "Cytokines produced by the Th2-type CD4 + T cells (interleukin (IL-4, IL-5, IL-13) in asthma have a central role in orchestrating the inflammatory response." (PMID 25890178, 2015). "Of these, IL-1 is an important mediator of many inflammatory diseases, and IL-4 and IL-13 are key regulators of asthma." (PMID 25658604, 2015). "Neutralizing antibodies to IL-4Rα and IL-13, such as dupilumab and lebrikizumab, respectively, do show promise in clinical effectiveness but only in select patients with typical Th2-type asthma." (PMID 26635789, 2015). "The role of IL-13 in mediating phenotypes of asthma was also supported by reports of increased IL-13 in lungs of asthmatic patients." (PMID 25848896, 2015). "The association between pendrin and inflammatory airway disease was first proposed in 2005, when it was observed that pendrin expression was upregulated in three different murine asthma models, including transgenic overexpression of IL-13 in lung." (PMID 26612971, 2015). "We demonstrate that the levels of IL-17A synthesis in the PBMC cultures negatively and IL-13 synthesis positively correlate with the absolute change in lung function (FEV1) after 2 weeks of oral prednisolone treatment in our adult asthma cohort." (PMID 25772594, 2015). "This would enable higher responses to low levels of IL-17A, IL-4 and IL-13 and thus contribute to more marked inflammatory effects such as those seen in severe asthma." (PMID 25849622, 2015). "All these were associated to a Th2-type cytokine profile (with the production of IL-5, IL-13 and IL-4), which is important for the development and maintenance of the Th2 response characteristic of asthma." (PMID 25890178, 2015).
asthma (continued). "We determined the levels of 6 cytokines implicated in asthma, which can be divided by the response profiles Th1 (TNF-α and IL-6) and Th2 (IL-4, IL-13, IL-10, and IL-5)." (PMID 26101464, 2015). "Possible molecular targets, at least in asthma, are IL-4 and IL-13, both involved in atopy related inflammatory processes, and partly sharing the same receptor." (PMID 26101468, 2015). "In mouse models of both allergic and respiratory virus induced-asthma, CLCA1 (previously known as mCLCA3 or gob-5) expression has been solidly linked to IL-13 driven MCM and controversially linked to AHR, both hallmarks of asthma and COPD." (PMID 26612971, 2015). "A recent study found that during experimental asthma, ILC2 proliferate and produce IL-13, which contributes to allergy and worsen the condition of asthma." (PMID 26289446, 2015). "For instance, ILCs type 2 producing IL-13 participate to disease pathology in experimental models of allergic asthma and virus-induced asthma exacerbation." (PMID 25950701, 2015). "Mouse models of asthma support the roles of IL-4, IL-5, and IL-13 in disease development, as knockout mice for these cytokines show reduction in overall asthma symptoms." (PMID 26346739, 2015). "The asthma severity node was strongly connected with mast cell mediators, tryptase, chymase, and carboxypeptidase A3 and with IL-13– and IFN-γ–secreting CD8+ cytotoxic T cells (TC2 and TC1 cells, respectively)." (PMID 25746968, 2015). "This suggests that IL-13 is an important marker for monitoring of evolution and success of therapy in patients with asthma." (PMID 27275233, 2015). "A wealth of inflammatory mediators, particularly the Th2-associated cytokines IL-4, IL-5, and IL-13, and the pro-inflammatory mediator TNF-α, contributed substantially to airway inflammation in asthma." (PMID 26343632, 2015). "Children in Class 5 (all of whom produced high levels of IL‐13, and almost all produced high levels of IL‐5, with some production of IL‐10 and IFN‐γ) had a fivefold increase in the risk of asthma." (PMID 26061524, 2015). "By contrast, compared to eosinophil-normal asthma (eosinophils≤0.3%), eosinophil-high asthma (eosinophils>0.3%) had higher levels of IL-5, IL-13, IL-16, and PDGF-bb, but same neutrophil percentage, IL-8, and FEV1." (PMID 26011707, 2015). "MiR-126 has also been found to be upregulated in the airway of an asthma mouse model, and its suppression reduces inflammation, expression of Th2 cytokines (e.g., IL-5 and IL-13), and airway hyperreactivity." (PMID 26418311, 2015). "Similar effects were seen from lebrikizumab (Genentech), an antibody blocking IL-13 in humans with Th2hi endotype asthma." (PMID 26346739, 2015). "Intriguingly, we observed that asthma mice treated with CaeA exhibited significant reduction in IL-5 and IL-13 levels in the BALF, as well as in the lungs." (PMID 26481184, 2015). "As antibody array showed that mangiferin suppressed characteristic cytokines secreted by Th1/Th2 cells such as IFN-γ, IL-12 and IL-4, IL-5, IL-13, which played the key roles in asthma." (PMID 24955743, 2014). "Let-7a negatively controls IL-13, a cytokine essential for allergic lung disease, an experimental model of asthma." (PMID 25594007, 2014). "In asthma, there seems to be an increased expression of Th2 cytokines, with an elevated production of IL-4, IL-5 and IL-13." (PMID 24450480, 2014). "Th2 cells, which are characterized by IL-4, IL-5, IL-9 and IL-13 cytokine production, predominate in asthma, whereas Th1 cells producing IFN-γ, IL-2 and TNF have rarely been associated with asthma." (PMID 25132806, 2014). "In humans with asthma, morphological and inflammatory changes are accompanied by increases in lung IgE, IL-4, IL-5, and IL-13." (PMID 24723965, 2014). "Loss of LLF GGT activity in the mutant GGTenu1 mouse causes an increase in baseline LLF glutathione content which is magnified in an IL-13 model of allergic airway inflammation and protective against asthma." (PMID 25132819, 2014).
asthma (continued). "They further identified patients with distinctly higher levels of IL-5 and IL-13, termed Th2-high asthma." (PMID 26557245, 2014). "It is well documented that interleukin-13 (IL-13) is an inducer of goblet cell differentiation in both human and murine airways and this IL-13 induced differentiation has been suggested to explain the goblet cell hyperplasia in asthma." (PMID 24533135, 2014). "In contrast to the findings in models of asthma and trauma, the Th2 cytokine IL-4 was unchanged and IL-13 was upregulated indicating the activation of both Th1 and Th2 cell signaling by electroacupuncture." (PMID 24732949, 2014). "In our study, it has been found that BMMCs from asthma rat models had many differences compared to normal rats, including higher levels of β-hexosaminidase released and higher cytokines (IL-6, IL-13, TNF-α, histamine) secreted." (PMID 24995695, 2014). "A majority of asthma phenotypes, including airway eosinophilia, airway hyperresponsiveness, and airway remodeling, are attributable to the pluripotent effects of IL-13 and its downstream molecules." (PMID 25344652, 2014). "IL-13 is a well described pro-inflammatory cytokine that drives inflammation in a mouse model of experimental asthma." (PMID 25132819, 2014). "Th2 cytokines such as IL-4, IL-5, and IL-13 play an important role in the pathophysiology of asthma, including AHR and airway wall remodeling." (PMID 25180025, 2014). "This suggests that commonly used markers for asthma, including IL-13 and chitinase, do in fact only reflect central airway inflammation." (PMID 24993465, 2014). "Induction of CHIA is via a TH2 specific, IL-13 mediated pathway, and has been implicated in TH2 dominated disorders such as asthma." (PMID 25074012, 2014). "The cytokine profile in asthma is typified by interleukin (IL-) 4, IL-5, and IL-13 that are typical Th2 cytokines." (PMID 24637581, 2014). "Nucleotide substitution in promoter region and ORF of IL4 receptor, IL13, HLA-II alleles, RANTES and CC-chemokine ligands were found to be strongly associated with asthma." (PMID 24409194, 2014). "Type-2 innate lymphoid cells proliferate and release interleukin-13 during protective immunity to helminth infection and detrimentally during allergy and asthma." (PMID 25088770, 2014). "As allergic, IL-13 driven, asthma is the primary indication for therapeutic STAT6 siRNA, our rationale for this approach was based on findings that respiratory allergy is reflective of an integrated, systemic inflammatory disorder." (PMID 24587331, 2014). "The results indicated that Th2 cytokines (IL-4, IL-13, and IL-5) were increased in mice with chronic-induced asthma (P<0.05) when compared with saline mice." (PMID 24637581, 2014). "IL-13 is another important factor; in a mouse model of airway effects due to asthma, eosinophilia was markedly inhibited by neutralization of IL-13." (PMID 25326908, 2014). "Group 2 innate lymphoid cells (ILC2s) release interleukin-13 (IL-13) during protective immunity to helminth infection and detrimentally during allergy and asthma." (PMID 25088770, 2014). "In severe asthma, the largest change (110-fold) is observed in Ifnγ expression followed by Il13, Il2, Il4, Il10, Il6, Il5, and Tnfα, respectively." (PMID 23781124, 2013). "IL-13 and IL-33 are known to drive eosinophil maturation and infiltration, mucus production and bronchial hyperreactivity." (PMID 23738146, 2013). "In our data, the interactive effects are consistent with IL-13 genotypes and household carpet use on asthma phenotypes." (PMID 23382814, 2013). "Two members of this gene cluster, IL-4 and IL-13, have been shown to have a role in the pathogenesis of asthma." (PMID 23865080, 2013). "IL-4 and IL-13, which are key cytokines in the pathogenesis of asthma, are involved in airway remodeling, inflammatory processes, airway hyperresponsiveness, goblet-cell hyperplasia, eosinophil infiltration, mucus hypersecretion, and B cell activation." (PMID 23451048, 2013).